CCL5 (C-C motif chemokine ligand 5)
Diseases named in the same sentence as CCL5 in open-access papers (continued):
Sharing a sentence is not in itself a finding about the gene and the disease.
breast cancer (continued). "Taken together with these previous studies and our findings, CCL5 secreted by stromal cells may contribute to tumor progression by activating CCR3 expressed in carcinoma cells and regulating downstream pathways such as ERK signaling in breast carcinoma tissues." (PMID 33671956, 2021). "Indeed, a recent study demonstrated that inducible IκB kinase-related (IKK-related) kinase IKBKE promotes in triple negative breast cancer cells the expression of IL-6 and CCL5, which in turn sustain the proliferation and migration of breast cancer cells in 3D culture." (PMID 29707128, 2018). "However, tumor-derived CCL5 apparently does not contribute to breast cancer progression." (PMID 27027351, 2016). "Among the inversely correlated genes were four chemokines, CCL5, CXCL9, CXCL10 and CXCL11 indicating that IRX2 might be actively involved in the regulation of chemokine secretion by mediating the transcriptional repression of these chemokines in breast cancer cells." (PMID 26560478, 2015). "In addition, there are other GPCRs and ligands that may recruit Tregs, such as CCR5/CCL5 in colorectal cancer (CRC) and pancreatic cancer, CCR6/CCL20 in HCC and breast cancer, and CCR10/CCL28 in ovarian cancer, while CXCR3 and CXCR6 are expressed by Tregs infiltrating renal cell carcinoma." (PMID 25110692, 2014). "The tumor-promoting activities of the inflammatory mediators CCL2 & CCL5 and TNFα & IL-1β in breast cancer are not fully overlapping (references above), therefore their coordinated expression may eventually provide advantage to the developing and metastasizing tumor." (PMID 21486440, 2011). "Thus, the context-dependent expression of the CCL5/CCR1 axis shown in the 3D co-spheroids may act as a tumor-promoting factor when tumor cells and mammary fat cells come into close contact in a 3D environment, as is the case with the infiltration of breast cancer cells in adjacent adipose tissue." (PMID 37444610, 2023). "As for SLC16A6, CCL5, and MAL2, their protein expression was almost negative in breast cancer tissues based on the results of the HPA database." (PMID 36341328, 2022). "Although in some breast cancer lines (MDA-MB-231 and MDA-MB-435) chronic hypoxia increases CCL5/RANTES expression, it does not affect it in the MCF-7 line." (PMID 32781743, 2020). "CCL5 and CCR5 (but not CCR1 and CCR3) are overexpressed in the basal and HER-2+ breast cancer subtypes." (PMID 29216863, 2017). "CCL5 and CCR5 are overexpressed in basal and HER-2+ breast cancer subtypes, but not in normal breast epithelial cells." (PMID 27335323, 2016). "Next, we compared the three groups of breast cancer patients (DCIS, IDC-no-relapse, IDC-with-relapse) with respect to the incidence of expression of CCL2, CCL5, TNFα and IL-1β in the tumor cells." (PMID 21486440, 2011). "An earlier study, which targeted women from the central coast of Tunisia, revealed that CCL5 rs2107538 had also been correlated with triple-negative breast cancer (TNBC) and hormone receptor-positive BC." (PMID 38001676, 2023).
COVID-19 (198 papers, 2020 to 2026). A disease caused by infection with severe acute respiratory syndrome coronavirus 2. "This study was conducted to investigate the associations between polymorphisms in the TNF-α, IL-6, IL-8, IL-10, and CCL5 genes and COVID-19 severity." (PMID 40881695, 2025). "While CCL5 is widely recognized for promoting immune cell migration and has been implicated in chronic diseases, cancers, and viral infections such as COVID-19, it also possesses antioxidant and tissue-repair functions under specific pathological conditions." (PMID 40563378, 2025). "(2022) showed that low CCL5 expression levels in the upper respiratory tract are associated with COVID-19 severity." (PMID 39483459, 2024). "(2022) who reported that high levels of CCL5 were associated with better outcomes in COVID-19 patients." (PMID 37389217, 2023). "In severe cases, through inflammatory mediators like IFN-α, IL-1β, IL-6, CCL2, CCL5 and others, COVID-19 causes an inflammatory process that if uncontrolled evolves into lung tissue injuries, systemic inflammations and pathogenesis, and organ failure." (PMID 37662953, 2023). "All CCR4 ligand chemokines are shown to be involved in COVID-19 associated immunity; however, it is more common for all of them, except RANTES/CCL5 and MDC/CCL22, to show elevated concentrations in blood plasma." (PMID 37685890, 2023). "This review describes the role of the CCL2/CCR2 and CCL5/CCR5 chemokine pathways associated with amplification of inflammatory responses in COVID-19 and the role of CVC in inhibiting this pathway." (PMID 35749425, 2022). "In conclusion, both asymptomatic SARS-CoV-2 infected blood donors and patients with severe COVID-19 share an inflammatory profile; however, high levels of IL-6, IL-10, and CCL5 were significantly associated with severe infection outcomes." (PMID 36287506, 2022). "Chronic inflammation and increased cytokine production, like TNF-α, IL-6, and CCL5, are critical features of COVID-19 patients, which suggests that they cause severe lung injury, multi-organ failure, and poor prognosis." (PMID 33804769, 2021). "However, carriers of the IL-10 (rs1800872, rs1800871) and CCL-5 (rs2107538) gene variants were associated with patients who died from COVID-19." (PMID 40881695, 2025). "The binding of unregulated CCL5 production in COVID-19 patients might minimize the risk of severe lung damage caused by inflammatory reactions, resulting in lower morbidity and mortality." (PMID 39065649, 2024). "In our study, elevated levels of IL-6, IL-10, and CCL5 seemed to be remarkable biomarkers for differentiating patients with severe COVID-19 from AS and NI patients, suggesting an association with progression to severe COVID-19." (PMID 36287506, 2022). "Peripheral blood levels of CCL5 were found to become elevated before IL-6 in severe COVID-19 patients." (PMID 40362649, 2025). "Recently, the CCL5/CCR5 axis was reported to participate in the response to COVID-19, HIV and tuberculosis." (PMID 40881695, 2025). "Thus, enhancing CCL5 expression early in COVID-19 may reduce the risk of severe illness." (PMID 41155463, 2025). "SNPs in the TNF-α, IL-6, IL-8, IL-10, CCL5 and CXCL6 genes have been associated with COVID-19 outcomes and with serum cytokine and chemokine levels." (PMID 40881695, 2025). "In a recent publication, we developed epidemiologically relevant effects of chronic CCL5/RANTES vehiculation in BMDJ/FDOJ on acute COVID-19 CCL5/RANTES cytokine storms." (PMID 40426971, 2025). "While the literature on CCL5 in COVID-19 remains inconclusive, several studies have documented reduced CCL5 levels in critically ill patients compared to those with mild disease." (PMID 41217548, 2025). "The aim of this work was to evaluate the associations of polymorphisms in the TNF-α, IL-6, IL-8, IL-10, CCL5 and CXCL6 genes with COVID-19 outcomes and with the serum levels of IFN-α, IFN-γ, TNF-α, IL-1Ra, IL-6, IL-7, IL-10, CCL2, CCL3, CXCL8, CXCL10 and GCSF." (PMID 40881695, 2025).
COVID-19 (continued). "In the culture supernatant of PBMCs from healthy participants, bLf decreased IL-6 levels and increased CCL5 in COVID-19 participants." (PMID 39483459, 2024). "The upregulation of CCL5 has been related to cytokine storm, and high levels of CCL5 in plasma have been found in critical COVID-19 patients." (PMID 38731851, 2024). "Specifically, compared to healthy controls, genes marking effector and cytotoxic CD8 T cell profiles (GZMB, NKG7, GZMH, PRF1, and CCL5) were upregulated in severe dengue and downregulated in severe COVID-19." (PMID 38294906, 2024). "Although CXCL8 levels were unaltered in both groups, high levels of CCL5 were detected after bLf treatment at 10 mg/mL in the COVID-19 group." (PMID 39483459, 2024). "In moderate COVID-19, we observed differential outflow of fewer inflammatory cytokines, including CCL5 and CCL23." (PMID 39187683, 2024). "The levels of proinflammatory cytokines and chemokines (IL-8, IL-18, CCL5) were higher in males with severe COVID-19, and the T cell response was less robust than that in females." (PMID 39507250, 2024). "Sex differences in the immune response to COVID-19 have previously been described, where higher levels of proinflammatory markers such as IL-8, IL-18, and CCL5 were found in the serum of males with COVID-19 than in females." (PMID 39507250, 2024). "Meanwhile, an increase of CD4+ T cells expressing CD69+ together with CCL5 levels was noted in our experiments using bLf on COVID-19 samples." (PMID 39483459, 2024). "In conclusion, a higher expression of CCL5 was found in the peripheral blood of mild COVID-19 cases in contrast to the upper airway." (PMID 39590591, 2024). "We found that NKG7, IL32, GZMA, PRF1, CST7, GZMH, and CCL5 were among the top DEG downregulated in CD3+ upon nasal Foralumab treatment of COVID-19 subjects." (PMID 36881624, 2023). "Severe cases of COVID-19 are associated with prolonged, heightened levels of cytokines, such as IL-6, IL-8/CXCL8, CXCL9, CXCL10, TNF-α, MCP1/CCL2, RANTES/CCL5, IL-18, and MIP-1α/CCL3, which can last for up to two months." (PMID 36983995, 2023). "Vector analysis conducted in the 1st trimester indicated that CXCL8, CCL3, CCL5, IL-1β, TNF-α, IL-12, IL-15, IL-1Ra, IL-10, and G-CSF were associated with convalescent COVID-19 in pregnant women." (PMID 37122732, 2023). "During COVID-19, infected airway epithelial cells increase production of CCL5 that functions as chemotactic molecule by binding to CCR528." (PMID 36702907, 2023). "Along with the upregulation of inflammatory mediators such as IL1B, TNF, and IL6, the downregulation of CCL5 can be a major contributor to COVID-19-mediated neuroinflammation." (PMID 37686360, 2023). "Research found that patients with COVID-19 showed higher serum concentrations of RANTES/CCL5 and observed “chemokine signature”." (PMID 35464423, 2022). "In the patients with moderate COVID-19, CD8+ TTE cells showed higher expression of IFNG, TNF, CCL5, PRF1, GZMB, and GZMA, together with genes encoding cytotoxic receptors (KLRB1, KLRC1, and KLRD1) in comparison with severe cases." (PMID 36119105, 2022). "According to a recent study, the levels of CCL4 and CCL5 were increased in all three groups of patients suffering from COVID-19, namely, mild, severe, or fatal, but these chemokines were significantly higher only in mild cases." (PMID 36016187, 2022). "Mon HLA and Mon CD14 inside Delta samples differ in expression for the cytokine panel (CCL3, VEGFA, CCL5, CCL4, CXCR4, IL7R, CXCL8, and PF4) that have been found associated with COVID-19 severity and mortality." (PMID 36230912, 2022). "Another hub gene CCL5 was an important hub gene involved in RA and COVID-19 and played an important role in inflammation and immune responses." (PMID 35464423, 2022). "In this regard, it has been discussed that high production of some chemokines, such as CXCL8/IL-8, CCL-2/MCP-1, CCL3, CCL5, CXCL9, and CXCL10 are associated with lung damage and COVID-19 severity." (PMID 36685603, 2022).
COVID-19 (continued). "Six hub genes (FCGR3A, CD69, IFNG, CCR7, CCL5, and CCL4) were closely associated with COVID-19 and HF." (PMID 36420258, 2022). "We observed activation of NF-κB signaling and activation of target genes, TNF-α, IL-6, and CCL5, following exposure of hepatocytes to exosomes isolated from plasma of COVID-19 patients." (PMID 33804769, 2021). "It has been shown that in patients with severe COVID-19 treatment with leronlimab reduces elevated plasma IL-6 and chemokine ligand 5 (CCL5), and normalized CD4/CD8 ratios." (PMID 33521616, 2021). "Some of these factors, along with PaO2/FiO2 index, the incidence of acute kidney injury (AKIN), co-infections, APACHE-II score, IFN-γ, IL-15, and CCL5, also contributed to differentiate the entire COVID-19 cohort from pandemic influenza A(H1N1) subjects." (PMID 33995342, 2021). "The increase in blood concentrations of different cytokines such as interleukins and chemokines such as IL-6, IL-8, IL-10, TNF-α, IL-1β, IL-2, IP-10, MCP-1, CCL3, CCL4, and CCL5 has been described for COVID-19 patients." (PMID 34262570, 2021). "Multiple-fold increases in CCL5 expression in severe COVID-19 patients compared to healthy individuals are well documented." (PMID 34975885, 2021). "The cytokines interleukin 6 (IL-6), interleukin 1 beta (IL-1β), tumor necrosis factor alpha (TNF-α) and chemokine C–C motif ligand 2 (CCL2), 3 (CCL3), and 5 (CCL5) are upregulated and represent potential targets for treatment of patients with COVID-19." (PMID 33521616, 2021). "Analyses performed in the BAL fluids showed that the chemokines CCL3 and CCL5 and the proinflammatory molecules IL-1β and IL-6 were significantly higher in patient 1 compared to the non-COVID-19 bLTx patient." (PMID 33801959, 2021). "In regard to cytokines and chemokine expression between COVID-19 cases we found that the highest avg (log2) values showing fold change were indicated by CCL5, IL1R2, NAMPT and PPBP." (PMID 34824360, 2021). "A recent study reported that leronlimab reduced the inflammation, plasma viremia levels, and T cell lymphocytopenia via blocking the CCL5/RANTES-CCR5 pathway in COVID-19 patients." (PMID 32784499, 2020). "COVID-19 patients had lower levels of most classical inflammatory cytokines (G-CSF, CCL20, IL-1β, IL-2, IL-6, IL-8, IL-15, TNF-α, TGF-β), but higher plasma concentrations of CXCL10, GM-CSF and CCL5, compared to non-COVID-19 patients." (PMID 33272291, 2020). "In addition, sera from COVID-19 patients contain pro-NETotic factors such as RANTES (CCL5) and platelet factor 4 (PF4), likely secreted by hyperactivated platelets and their precursor megakaryocytes, which are known to harbor SARS-CoV-2." (PMID 41596316, 2026). "CCL5 levels negatively correlate with mortality in COVID-19, suggesting that it may protect against severe disease progression." (PMID 41155463, 2025). "CCL5 has been described as the optimal indicator of COVID-19 severity." (PMID 41155463, 2025). "The rs21075238 is located at the binding site for GATA binding protein 2 (GATA2), which is involved in the transcriptional regulation of proinflammatory cytokines therefore, CCL5 might participate in the COVID-19 inflammatory process." (PMID 40881695, 2025). "Single nucleotide polymorphisms (SNPs) in the TNF-α, IL-6, IL-8, IL-10, CCL5 and CXCL6 genes have been found to be associated with COVID-19 severity, suggesting that SNPs could help explain COVID-19 outcomes." (PMID 40881695, 2025). "The observation that lower CCL5 levels predict worse outcomes challenges the hyperinflammatory state hypothesis of COVID-19 mortality." (PMID 41217548, 2025). "In COVID-19 cases, CCL5 might play an important role in controlling the immune cell circulation at the first stage of infection, avoiding excessive recruitment in the airways." (PMID 39590591, 2024). "Studies performed on CCL5 with COVID-19 should be considered with caution." (PMID 38731851, 2024).
COVID-19 (continued). "In addition, it has been reported that in the early phase of SARS-CoV-2 infection, serum CCL5 levels are increased in patients with mild symptoms of COVID-19 compared to severe patients." (PMID 39281667, 2024). "It was suggested earlier that serum levels of IL-10 along with interleukin 1Ra (IL-1Ra, synthesized in monocytes and keratinocytes) and C-C motif chemokine ligand 5 (CCL-5) at early stages of progression may predict the severity of COVID-19." (PMID 39273582, 2024). "Among chemokines, CCL5 has been related to cytokine storm in severe COVID-19 cases." (PMID 38731851, 2024). "For example, previous research has shown that the COVID-19-associated ARDS exhibited higher levels of plasma CCL5, CXCL2, and CXCL10 compared to the non-COVID-19 ARDS patients." (PMID 38745657, 2024). "However, other studies found a higher expression of CCL5 in critical COVID-19 patients, suggesting a role prompting inflammation disorders." (PMID 37389217, 2023). "A recent study demonstrated that CCL5 contributes to the recruitment of inflammatory cells (mainly T cells and macrophages), and blockading CCR5 signaling using leronlimab (a monoclonal antibody) has been conducted to treat COVID-19-associated cytokine storms." (PMID 37936693, 2023). "In particular, T cell subpopulations target receptors on other cells via CCL5 and may play an important role in patients with COVID-19-induced ARDS." (PMID 37363730, 2023). "In particular, T cell subsets target receptors on other cells via CCL5 and may play an important role in patients with COVID-19-induced ARDS." (PMID 37363730, 2023). "In aggregated analysis, Eotaxin-3 and Eotaxin-1 levels decreased in COVID-19 patients; however, in sex-segregated analysis, Eotaxin-3, CCL5, IL-21, and IL6+CD4+ T cell levels were lower in female versus male HCW and this sex difference was maintained in female versus male COVID-19 patients." (PMID 37998327, 2023). "We therefore predict that each of the CCR2 and CCR5 receptors has a complementary role in infection-associated inflammation and tissue sequelae in COVID-19 with CCR2/CCL2 seen in both early and late stages of infection and CCR5/CCL5 seen later in the infectious process." (PMID 35749425, 2022). "Regarding correlations, zonulin was found to be directly correlated with creatinine, D-dimer values, and prothrombin time, all of which have previously been associated with poorer outcome in hospitalised COVID-19 patients and inversely correlated with CCL5/RANTES and Sa/FiO2." (PMID 36147602, 2022). "SARS-CoV-2 infection induced CCL2, CCL5 and IL-6 release from placental cells, which might promote the cytokine storm in pregnant women with COVID-19." (PMID 36414950, 2022). "In a follow-up study testing COVID-19 patients for 34 inflammatory-related substances, patients with mild symptoms showed higher levels of chemokine RANTES (CCL5), while patients with later-stage disease had significant increases in cytokines such as interleukin (IL) 6 and interferon-γ (IFN-γ)." (PMID 36248790, 2022). "Furthermore, high levels of CCL5 cause liver disorders and acute kidney injury (AKI) in COVID-19 patients." (PMID 34975885, 2021). "Therefore, this network also displays the contribution of increased pro-inflammatory molecules or signaling pathways (IL1B, IL6, IL8, IL17a) and upregulated chemokine signaling (CXCR4 signaling, CCL5) observed in severe COVID-19 outcomes." (PMID 33941085, 2021). "We observed that the pulmonary environment of mild COVID-19 patients induced the upregulation of only five pro-inflammatory genes in MSCs, which code for the chemokines CCL5 and XCL2, plus TRAF1, which has already been identified as an important inflammatory mediator in the lungs." (PMID 35095855, 2021). "COVID-19 patients who succumb to pneumonia and hypoxia had one hallmark feature of the profound inflammatory state that marked elevation of serum inflammatory cytokines (IL-6, IFN-γ, IL-1β, TNF-α and TGF-β) and chemokines (CCL2, CCL5, CXCL8 and CXCL10)." (PMID 34313585, 2021).